ACVR2A (activin A receptor type 2A)
Description:
On ligand binding, forms a receptor complex consisting of two type II and two type I transmembrane serine/threonine kinases. Type II receptors phosphorylate and activate type I receptors which autophosphorylate, then bind and activate SMAD transcriptional regulators. Receptor for activin A, activin B and inhibin A. Mediates induction of adipogenesis by GDF6 (By similarity).
Synonyms: ACVR2; ACTRII
Tractability: Small molecule: a structure with a bound ligand is known; a high-quality ligand is known; it belongs to a druggable protein family. Antibody: its Gene Ontology location is reachable by antibodies, with high confidence; UniProt places it where antibodies can reach, with medium confidence; UniProt predicts a signal peptide or a membrane-spanning region. PROTAC: ubiquitination databases record sites on it; its protein half-life has been measured; a small molecule that binds it is known. Other modalities: an approved drug acts on it.
Target class: Kinase; TKL protein kinase STKR family; Protein Kinase; Enzyme; TKL protein kinase group; TKL protein kinase STKR Type 2 subfamily
Gene: Protein-coding gene on chromosome 2 (147,844,378 to 147,930,826, forward strand). Ensembl gene ENSG00000121989.
Subcellular location: Cell membrane
Subcellular location (Human Protein Atlas): Cytosol
Pathways (Reactome):
Signal Transduction: Signaling by Activin; Signaling by BMP; TGFBR3 regulates activin signaling
Developmental Biology: Regulation of signaling by NODAL; Signaling by NODAL
Gene Ontology:
Molecular function: activin binding; activin receptor activity; activin receptor activity, type I; activin receptor activity, type II; coreceptor activity; protein binding; protein serine/threonine kinase activity; transmembrane receptor protein serine/threonine kinase activity; BMP receptor activity; ATP binding; growth factor binding; identical protein binding; inhibin binding; PDZ domain binding; protein kinase activity
Biological process: activin receptor signaling pathway; BMP signaling pathway; cellular response to BMP stimulus; osteoblast differentiation; positive regulation of activin receptor signaling pathway; positive regulation of bone mineralization; positive regulation of erythrocyte differentiation; positive regulation of osteoblast differentiation; positive regulation of protein phosphorylation; positive regulation of SMAD protein signal transduction; positive regulation of transcription by RNA polymerase II; cell surface receptor protein serine/threonine kinase signaling pathway; cellular response to growth factor stimulus; negative regulation of ossification; pattern specification process; developmental process
Cellular component: cytoplasm; inhibin-betaglycan-ActRII complex; receptor complex; activin receptor complex; plasma membrane; cell surface; membrane
Genetic constraint (gnomAD): Loss-of-function variants: 7 observed, 59.16 expected, observed/expected ratio (o/e) 0.12, 90% interval 0.066 to 0.22. The upper end of that interval is the gene's LOEUF score, 0.22, which puts it in group 1 of 6, group 1 being the genes least tolerant of losing a copy. Missense variants: 307 observed, 633.02 expected, observed/expected ratio (o/e) 0.48, 90% interval 0.44 to 0.53. Synonymous variants: 187 observed, 212.4 expected, observed/expected ratio (o/e) 0.88, 90% interval 0.78 to 0.99.
Cancer hallmarks: suppression of growth (promotes); proliferative signalling (promotes); genome instability and mutations (promotes); invasion and metastasis (promotes); escaping programmed cell death (promotes)
Homologues: Orthologues: chimpanzee ACVR2A (100% identical), macaque ACVR2A (100% identical), mouse Acvr2a (99% identical), rabbit ACVR2A (99% identical), rat Acvr2a (99% identical), pig ACVR2A (98% identical), guinea pig ACVR2A (94% identical), tropical clawed frog acvr2a (88% identical), zebrafish acvr2aa (80% identical), dog ACVR2A (73% identical), zebrafish acvr2ab (66% identical), Drosophila melanogaster babo (30% identical), and 3 more. Paralogues in human: ACVR2B (67% identical), BMPR2 (35% identical), TGFBR2 (34% identical), TGFBR1 (30% identical), ACVR1C (30% identical), BMPR1A (30% identical), BMPR1B (29% identical), ACVR1B (29% identical), ACVRL1 (28% identical), AMHR2 (28% identical), ACVR1 (27% identical).
Diseases named in the same sentence as ACVR2A in open-access papers:
ACVR2A is named in the same sentence as 92 diseases in open-access papers, as found by Europe PMC text mining. Sharing a sentence is not in itself a finding about the gene and the disease. The quoted sentences say what the papers report.
colon cancer (15 papers, 2008 to 2025). "ACVR2A (activin A receptor type 2A) has a mutation rate of about 60%, making it the most frequently mutated gene in hypermutated colon cancer." (PMID 35723313, 2022). "TGFBR2 and ACVR2A are commonly mutated in microsatellite unstable (MSI) colon cancers, which is the second most common genomic subtype." (PMID 26497569, 2015). "Mutations of ACVR2A are commonly found in unstable colonic cancers, and interestingly, infiltration of CD3 T cells is associated with mutated ACVR2A genes." (PMID 22980038, 2012). "Loss of ACVR2A has been implicated in the advancement and metastasis of colon cancer." (PMID 38898042, 2024). "The ACVR2A mutation was found in hypermutation colon cancers, which was also identified in sRL-CCs." (PMID 34422903, 2021). "Additional studies indicated that the activin A/ACVR2A axis promotes metastasis in colon cancer by selectively activating SMAD2." (PMID 40444773, 2025). "Consistent with an activin/PI3K/pAkt–induced p21 downregulation, we now show that in colon tumors of ACVR2A KO mice pAkt activation is diminished and p21 levels are restored." (PMID 26497569, 2015). "Both TGFBR2 and ACVR2A harbor coding microsatellites and mutations in MSI colon cancers which are associated with loss of protein expression." (PMID 26497569, 2015). "Using ACVR2A/TGFBR2 wild type FET colon cancer cells, FET with SMAD4 knockdown, and the SMAD4-null colon cancer cell line SW480, we found a SMAD4-independent increase in pAkt Ser473 after activin treatment compared to control and TGFβ treatment." (PMID 26497569, 2015). "In primary colon cancer tumors, we observed that nuclear p21 localization correlated with TGFBR2 expression while loss of nuclear p21 is associated with ACVR2A expression, respectively." (PMID 26497569, 2015). "Mitogenic signaling/growth factor receptor status and p21 localization were correlated in primary colon cancers and intestinal tumors from either AOM/DSS treated ACVR2A (activin receptor 2) −/− or wild type mice." (PMID 26497569, 2015). "ACVR2A is a member of the transforming growth factor-beta (TGF-β) family, involving the regulation of cell differentiation, migration, proliferation, and apoptosis of colon cancer." (PMID 35814400, 2022). "We have previously observed that loss of nuclear p21 expression correlates with either presence of ACVR2A or absence of TGFBR2 in primary colon cancers." (PMID 26497569, 2015). "However, in tumor tissue of ACVR2A KO mice, we observed a decrease in pAkt and an increase in p21 compared to normal tissue consistent with an activin/PI3K/Akt involvement in p21 downregulation in colon cancer." (PMID 26497569, 2015). "While there was a trend towards more intestinal cancers in the challenged ACVR2A knock outs compared to wild type mice, this was not statistically significant, underscoring the likely overlap/synergy of TGFβ family member signaling in colon cancer." (PMID 26497569, 2015).
colorectal cancer (11 papers, 2008 to 2025). A primary or metastatic malignant neoplasm that affects the colon or rectum. "In this study, we evaluated the effect of ACVR2A on angiogenesis associated with colorectal cancer cells." (PMID 38898042, 2024). "Interestingly, ACVR2A (encoding a TGF-β super-family differentiation factor) has been described to be recurrently mutated in MSI-positive colorectal cancer." (PMID 23237666, 2012). "We can see that the genes activin A receptor type 2A and 5XRCC6P5 are both related to colorectal cancer." (PMID 33816986, 2021). "This assertion is extracted from an article, which puts in relation the activin A receptor type 2A gene to the colorectal cancer and describes a drug—that is, Mesalazine—that reduces mutations in transforming growth factor of the gene." (PMID 33816986, 2021). "Thisstudy assessed one of these elements, the ACVR2A gene.Qualitative and quantitative analyses of the ACVR2A gene in 84patients with colorectal cancer was performed." (PMID 30856244, 2019). "For this reason, in the study, the expression of theACVR2A gene in patients with colorectal cancer was estimated.The level of ACVR2A expression for age and sex of respondents wasassessed." (PMID 30856244, 2019). "Also, the frequency of mutations seen here is comparable to the previously reported frequency in MSI-positive colorectal cancer and emphasizes the importance of ACVR2A and TGF-β signaling in MSI-positive GC, while unraveling the oncogenic roles of RPL22 and LMAN1 requires further investigation." (PMID 23237666, 2012). "To date, no studies have investigated the impact of ACVR2A expression on angiogenesis in colorectal cancer." (PMID 38898042, 2024).
preeclampsia (10 papers, 2011 to 2025). Preeclampsia is a hypertensive disorder of pregnancy that is characterized by new-onset hypertension with proteinuria presenting after 20 weeks of gestation, and depending on mild or severe forms may initially present with severe headache, visual disturbances, and hyperreflexia. "Pre-eclampsia (PE) is a serious pregnancy disorder linked to genetic factors, particularly the ACVR2A gene, which encodes a receptor involved in the activin signaling pathway and plays a critical role in reproductive processes." (PMID 40444773, 2025). "The MDR algorithm identified the genetic variant ACVR2A rs1014064 as interacting with age and BMI in association with preeclampsia among Filipino women." (PMID 30621627, 2019). "The MDR algorithm enabled the analysis of high-order gene/factor interactions and identified ACVR2A rs1014064 as important in modulating preeclampsia risk among older Filipino women with a middle-range BMI." (PMID 30621627, 2019). "Currently, only two preeclampsia susceptibility genes (ACVR2A, STOX1) have been identified within confirmed regions with significant genome-wide linkage, although many genetic screens in multiple populations have been performed." (PMID 21490791, 2011). "Large-scale family studies have identified associations between preeclampsia and genetic variations in ACVR2 (activin A receptor type 2A), ROCK2 (coiled-coil-containing protein kinase 2), ERAP1 (endoplasmic reticulum aminopeptidase 1), and ERAP2 (endoplasmic reticulum aminopeptidase 2)." (PMID 40507612, 2025). "The MDR algorithm identified an interaction between age, BMI and ACVR2A rs1014064, indicating that context among genetic variants and demographic/clinical factors may be crucial to understanding the pathogenesis of preeclampsia among Filipino women." (PMID 30621627, 2019). "Although ACVR2A plays a major role in human trophoblast differentiation and has been linked to preeclampsia susceptibility in humans, it is unclear how it could contribute to abnormal SCNT phenotypes." (PMID 22701625, 2012). "Only two preeclampsia susceptibility genes have been identified so far, ACVR2A and STOX1." (PMID 21490791, 2011). "Regarding the reproductive system, three of these genes (UBE2N, PPP2R1B and ACVR2A) have been shown to be involved in reproductive disfunctions in humans (polycystic ovary syndrome and transsexuality, azoospermia, and susceptibility to preeclampsia, respectively." (PMID 36340025, 2022). "Initial studies have shown a linkage between preeclampsia and various parts of chromosome 2, where the ACVR2A gene is localized." (PMID 30621627, 2019). "In the case of ACVR2A and ERAP2 we subsequently were able to demonstrate association with preeclampsia in the Norwegian population using other SNPs in these genes, providing evidence of different allele frequencies and LD patterns at these loci." (PMID 22432041, 2012). "Secondly, multiple studies have found increased Activin A in serum of preeclamptic women, making its receptor ACVR2A a very interesting protein in the development of preeclampsia." (PMID 21490791, 2011). "Finally, we investigated the presence of variants in four selected genes previously reported in relation to preeclampsia; the ROCK2, ACVR2A, ERAP1, and ERAP2 genes." (PMID 29758065, 2018).
bladder cancer (7 papers, 2019 to 2025). "It is noteworthy that ACVR2B expression increased significantly in human bladder cancers of both males and females, whereas ACVR2A expression was unchanged." (PMID 40144023, 2025). "Previously, researches demonstrated circRNA ACVR2A suppresses bladder cancer progression through regulating miR-626/EYA4 axis; CircRNA INTS4 promotes tumorigenesis in bladder cancer via miR-146b/CARMA3 axis." (PMID 33656636, 2022). "Circular ACVR2A expression was found to be suppressed in bladder cancer tissues and cell lines and has a functional role in bladder cancer inhibition and metastasis." (PMID 31973134, 2020). "In bladder cancer, circ-ACVR2A could directly interact with miR-626 and acts as a miRNA sponge to regulate EYA4 expression, thus inhibiting bladder cancer cell proliferation and metastasis." (PMID 33613544, 2020).
breast carcinoma (7 papers, 2011 to 2023). "BMP2, BMP4, GDF11 and TGFBR2 had relatively higher levels in bone metastases of breast cancer while BMP5, BMP7, BMPR2, BMPR1A and ACVR2A presented lower expression in the bone metastases, in the E-MTAB-4003 dataset." (PMID 37333824, 2023). "The TCGA data showed that young-age breast cancer patients have a lower level of expression of RANBP3L, GLYATL-1, and ESR1, whereas ACVR2A, SERPINE2, and PCDHGB7 have higher expression in young-age breast cancer patients compared to old age patients." (PMID 36672708, 2023). "We have previously reported that all six BMP specific receptors (ACVR1, BMPR1A, BMPR1B, ACVR2A, ACVR2B, and BMPR2) are uniformly expressed among the breast cancer cell lines studied here." (PMID 22118688, 2011).
gastric cancer (6 papers, 2012 to 2025). A primary or metastatic malignant neoplasm involving the stomach. "ACVR2A hyper-mutation in the tumor of patients with MSI was reported in Chinese patients with gastric cancers." (PMID 35814400, 2022). "In MSI-positive GCs, ACVR2A, RPL22, LMAN1, and STAU2 were observed to have recurrent single base thymine deletions in poly(T) regions and this was confirmed in a screen of an additional 94 gastric cancer/normal paired samples (9 MSI-positive)." (PMID 23237666, 2012).
myeloma (6 papers, 2013 to 2025). "Specifically, we found that healthy MSCs exposed to MM cells underwent gains (HOXA9, ACVR2A, EBF2) and losses (HOXA2, HOXA3, HOXC5) of DNA methylation in the direction of those observed for MSCs from myeloma patients." (PMID 33462210, 2021). "In myeloma cells, BMP-6- and BMP-9-induced activation of SMAD1/5/8 through ACVR2A/ACVR2B/ALK2 was inhibited by activin A treatment." (PMID 26047946, 2015). "Thus, ALK2, ACVR2A and ACVR2B are candidate mediators of the antagonizing effects of activin A on BMP-6 and BMP-9 signaling in myeloma cells." (PMID 26047946, 2015). "Moreover, ACVR2A, ACVR2B and ALK2 are ubiquitously expressed and knowledge about regulation of signaling through these receptors might have general implications, for instance in bone homeostasis in myeloma patients." (PMID 26047946, 2015). "In contrast to BMPR1a-FC, we found an activin ligand trap (ACVR2a-FC) to slightly increase osteoclastogenesis, demonstrating that BMP and activin inhibition have non-equivalent effects on myeloma bone disease in this model system." (PMID 31586071, 2019). "Using myeloma cell lines as a model system, we show that activin A antagonizes BMP-6 or BMP-9-signaling through ACVR2A/ACVR2B/ALK2, but not BMP-2 or BMP-4-signaling through BMPR2/ALK3 or BMPR2/ALK6." (PMID 26047946, 2015).
Obesity (6 papers, 2016 to 2025). Accumulation of substantial excess body fat. "This study further suggests that decoy ACVR2A/2B receptor drugs being considered for anti-obesity co-therapies with GLP1-agonist drugs might additionally involve the suppression of GDF3 signaling and warrant further exploration." (PMID 40360531, 2025).
anemia (5 papers, 2015 to 2021). A reduction in the number of red blood cells, the amount of hemoglobin, and/or the volume of packed red blood cells. "Sotatercept (ACE-011) is an activin receptor type IIA (ACVR2A) Fc fusion protein which is currently under phase 1/2 investigation for the treatment of cancer-associated anemia." (PMID 26384307, 2015). "Thus, when decoy receptors for ACVR2A or ACVR2B were used in clinical trials, activin A signaling was inhibited with improved anemia and bone disease." (PMID 26047946, 2015).
hepatocellular carcinoma (4 papers, 2016 to 2025). A malignant tumor that arises from hepatocytes. "Although ACVR2A mutations are prevalent in non-viral hepatocellular carcinomas (HCCs), the underlying mechanism remains unelucidated." (PMID 40139191, 2025).
liver cancer (3 papers, 2021 to 2025). An epithelial or non-epithelial malignant neoplasm that arises from the liver. "Mechanisms for the progression of NAFLD/NASH to liver cancer remain incompletely understood, pathogenesis could involve DNA damage of other loci, inflammatory response, genetic modifiers as PNPLA3 or TM6SF2 or mutations such as the recently reported ACVR2A mutations." (PMID 36587184, 2022).
lung carcinoma (3 papers, 2020 to 2025). "ACVR2A, ACVR1C, BMP4, and CHRDL2, on the other hand, was found to be commonly co-expressed with BMP5 in bladder, breast and lung cancer." (PMID 31973134, 2020).
ovarian carcinoma (3 papers, 2016 to 2019). A malignant neoplasm originating from the surface ovarian epithelium. "Inaddition, ovarian cancer patients with higher ACVR2A expression hadshorter disease-free survival compared to those with low expression." (PMID 30856244, 2019).
prostate carcinoma (3 papers, 2012 to 2016). A carcinoma that arises from epithelial cells of the prostate gland. "ACVR2A is a receptor for activin-A and controls cell proliferation, for example proliferation of prostate cancer cells." (PMID 22980038, 2012).
Sepsis (3 papers, 2014 to 2025). Sepsis is defined as life-threatening organ dysfunction caused by a dysregulated host response to infection. "The levels of ACVR2A were significantly higher in the severesepsis group than in the mild sepsis group, and were significantly higher in the septic shock groupthan in the severe sepsis group." (PMID 24303815, 2014). "Dynamic changes in serum ACVR2A, FOXO1, IHH and STK4 levels in patients with sepsis during theirhospitalization in ICUs were evaluated." (PMID 24303815, 2014). "Hence ACVR2A may affect sepsis processes by regulatingthe levels of IL-6 or TGF-β." (PMID 24303815, 2014). "This indicates thatthe levels of ACVR2A and FOXO1 were lower in patients with sepsis than in normal controls becausethey are the common target genes of miR-223, miR-15a andmiR-16." (PMID 24303815, 2014). "ROC analysis was then performed on ACVR2A, FOXO1, IHH and STK4 to evaluate the predictive valueof sepsis mortality." (PMID 24303815, 2014). "Levels of ACVR2A (P<0.01) and FOXO1(P<0.01) were significantly different among normal controls, patients withsepsis, patients with severe sepsis and patients with septic shock." (PMID 24303815, 2014). "Interestingly, the expression of Inhba, Smad3, Acvr1b, Acvr2a, Stat5a, and Stat5b was all higher in the macrophages of patients compared with healthy volunteers, suggesting that the activin A/Smad3/STAT5 axis is also involved in human sepsis." (PMID 40067393, 2025).